LINC01291 (long independently transcribed non-coding RNA 1291)
Synonyms: TCONS_00002938; AC104135.4; LINC01293
Gene: Long non-coding RNA gene on chromosome 2 (74,908,953 to 74,943,494, forward strand). Ensembl gene ENSG00000204792.
Diseases named in the same sentence as LINC01291 in open-access papers:
LINC01291 is named in the same sentence as 3 diseases in open-access papers, as found by Europe PMC text mining. Sharing a sentence is not in itself a finding about the gene and the disease. The quoted sentences say what the papers report.
melanoma (1 paper, 2022). A malignant, usually aggressive tumor composed of atypical, neoplastic melanocytes. "Mechanistically, LINC01291 functions as a competing endogenous RNA by sponging microRNA-625-5p (miR-625-5p) in melanoma cells and maintaining insulin-like growth factor 1 receptor (IGF-1R) expression." (PMID 33674778, 2022). "Collectively, the results suggest that LINC01291 functions as a miR-625-5p sponge in melanoma cells." (PMID 33674778, 2022). "The data identified LINC01291 as a cytoplasmic lncRNA in melanoma cells." (PMID 33674778, 2022). "LINC01291 was overexpressed in melanoma tissues than in adjacent normal tissues." (PMID 33674778, 2022). "However, to the best of our knowledge, the expression profile and functions of LINC01291 in melanoma remain unclear." (PMID 33674778, 2022).
tumor (1 paper, 2022). "The data indicate that LINC01291 was downregulated, whereas miR-625-5p was upregulated in the tumor xenografts originating from sh-LINC01291-transfected A-375 cells compared with those originating from sh-NC-transfected cells." (PMID 33674778, 2022).
LINC01291 also shares sentences with these, for which no sentence is quoted: preeclampsia (1 paper).